TNF (tumor necrosis factor)
Diseases named in the same sentence as TNF in open-access papers (continued):
Sharing a sentence is not in itself a finding about the gene and the disease.
Cachexia (continued). "It has been reported that decreased appetite and caloric intake are associated with increased synthesis of pro-inflammatory interleukins, mainly TNF-alpha, leading to cachexia." (PMID 35162195, 2022). "The fundamental stage in cachexia is most likely the systemic inflammatory response, followed by increased production of pro-inflammatory cytokines like TNF-α." (PMID 35159388, 2022). "In vitro and in vivo models of TNF-α-induced cachexia showed high ceramide levels during TNF-α treatment with increasing atrophy." (PMID 35328423, 2022). "Several studies have shown a possible role of TNF-alpha in Acquired Immune Deficiency Syndrome (AIDS) manifestations such as fever, fatigue, cachexia, aphthous ulcers and dementia." (PMID 36359281, 2022). "The metal-ion transporter ZRT- and IRT-like protein 14 (ZIP14) is reported upregulated by TNFα and ZIP14-dependent zinc accumulation induces MyHC loss in cachexia." (PMID 36618945, 2022). "It has been shown that different components of the ginseng including GE5, GE50, and Rb1 reduce the inflammation by reducing the TNF-α and IL-6 cytokine levels in cancer cachexia mice, thereby improving the symptoms of cancer cachexia." (PMID 35069931, 2022). "The main cytokines driving cachexia are IL-6, TNF-α, TGF-β and MIC-1/GDF15 MIC-1/GDF15, a member of the TGF-β superfamily, is produced in large amounts by normal and cancer cells." (PMID 36078078, 2022). "Several pro-inflammatory cytokines such as TNF-α, IL-6, IL-1, and interferon-γ (IFNγ), either tumor-derived or host-derived, were reported to be upregulated in cachexia." (PMID 35646636, 2022). "Among the molecular alterations accused of cancer-induced cachexia, TNF-α 308 G/A (rs1800629) and −1031T/C (rs1799964) are single-nucleotide polymorphisms (SNPs) within the gene encoding this pro-inflammatory cytokine." (PMID 34900737, 2021). "In cancer patients, the inflammatory cytokines produced by tumor cells and leukocytes like tumor TNF-α and IL-1, IL-6, and IL-8 are major drivers of cachexia, which affects several tissues, including skeletal muscle, brain, liver, and so on." (PMID 34760698, 2021). "The role of inflammation and cytokines has been discussed as being one of the main factors for the establishment of cachexia, in especial involving TNF-α and IL-6." (PMID 33413302, 2021). "Specifically, the inflammatory cytokines, IL-6, TNF-α and IL-1 have been implicated in CKD-associated cachexia." (PMID 34302016, 2021). "Accordingly, the significant role of the systemic inflammatory response mediated by TNF-α in the etiopathology of cachexia encourages investigating SNPs of TNF-α as cachexia-related risk factors." (PMID 34900737, 2021). "TNF-α is probably the most characterized cytokine in cachexia, as it promotes anorexia and skeletal muscle wasting mainly through the NF-κB pathway." (PMID 34900737, 2021). "The levels of TNF-α and IL-6 were significantly increased in the cachexia control group than in the normal control group (p < 0.01)." (PMID 34262449, 2021). "In the PC-dependent cachexia, Interleukin-1 (IL-1), IL-6, IL-8, and tumor necrosis factor α (TNF-α) have been recognized as the most involved factors." (PMID 34684523, 2021). "When TNFα is found in high concentrations, it is related to the cachexia typically observed in chronic infections by T. vivax, with anemia in T. brucei infections, and immunosuppression." (PMID 34827923, 2021). "The early review papers already indicate the ability of macrophage produced TNF-α to induce cachexia." (PMID 33557173, 2021). "Tumor derived pro-inflammatory cytokines including TNF, interferon-γ (IFN-γ), and several interleukins (IL-6, IL-1β) have been associated with the development and progression of cachexia." (PMID 34621740, 2021). "The condition cachexia is mimicked by co-exposure to TNFα and IFNγ, and it induces decreasing of the diameters of C2C12 myotubes, as seen in skeletal muscle atrophy." (PMID 34371902, 2021).
Cachexia (continued). "As such, cachexia is generally associated with increased levels of inflammatory molecules such as CRP, TNF-α, IL-6, and IL-8." (PMID 34830921, 2021). "We investigated the effects of HICA on mouse C2C12 myotubes under normal conditions and during cachexia induced by co-exposure to TNFα and IFNγ." (PMID 34371902, 2021). "Although our in vitro findings demonstrated a significant impact of L-carnitine on the TNF-α-induced C2C12 cell cachexia model and provided insight into the specific mechanism, drug metabolism in vivo is complex." (PMID 34724970, 2021). "Several studies have linked cachexia to increased plasma levels of proinflammatory cytokines such as interleukin (IL) 1β, IL6, tumor necrosis factor-alpha (TNF-α), and interferon-gamma (IFN-γ)." (PMID 32547603, 2020). "In the research on inflammatory cytokine-related cachexia, TNF-a, IL-1, IL-6, and IFN-gamma were all suggested to be related to cell death along with chronic diseases." (PMID 32486412, 2020). "Mice s.c. injected with LLC or B16 melanoma cells showed cachexia development, with reduced body weights, WAT loss, muscle wasting, and increased serum TNF-α and IL-6 levels." (PMID 33329046, 2020). "MyoD is a direct target of the NF-κB transcription factor activation cascade that is activated during cachexia by TNFα." (PMID 33613297, 2020). "The JAK-STAT pathway is vital in the regulation of pro-inflammatory cytokines such as IL-6 and TNF-α of which both have been shown to be involved in the modulation of cachexia." (PMID 32781663, 2020). "It is well-established that C26 cachexia alters the plasma levels of several soluble factors including TNFα, IL-1β and IL-6 which can accelerate the activity of key proteolytic pathways involved in the development of muscle weakness." (PMID 33014286, 2020). "TNF-α is involved in increased endothelia cell permeability, pyrexia, algesia, cachexia, and leukocyte production and activation to generate more prostaglandins (PGs)." (PMID 32090060, 2020). "Similar to WAT, we found that BAT IL-6 and TNF come exclusively from macrophages in the setting of cachexia." (PMID 32934774, 2020). "The positive effect of thalidomide on tumor repression is accompanied by the preservation of skeletal muscle fibers by reducing muscle expression of tumor-necrosis factor Tnf-α and transforming growth-factor Tgf-β, thereby preventing cancer-related cachexia." (PMID 33114658, 2020). "Higher levels of IL-6, IL-8, IL-1β and TNFα have been demonstrated in patients with confirmed cachexia." (PMID 33327591, 2020). "Among the different types of treatment that aim at reversing or restricting the progression of CC is the use of pharmacological interventions with anti-cachexia agents and the treatment of inflammatory cytokines designed to contain cachexia, especially TNFα." (PMID 33613297, 2020). "We found that GE5, GE50 and Rb1 can reduce the inflammatory cytokines TNF-α and IL-6 in cancer cachexia mice." (PMID 32020864, 2020). "TNFα, IL-6, IL-8, IL-1β, and IFNγ are considered to be the major inflammatory mediators of cancer-induced cachexia, which have been demonstrated to be elevated in various animal models of cancer." (PMID 32722688, 2020). "In PC-dependent cachexia, interleukin 1 (IL-1), interleukin 6 (IL-6) Interleukin 8 (IL-8), and tumor necrosis factor α (TNF-α) are the most common pro-inflammatory cytokines." (PMID 32466362, 2020). "Among the most relevant factors, interleukin (IL)-6, IL-1α, tumor necrosis factor-alpha (TNFα), and interferon-gamma (INFγ) have long been recognized as mediators of cancer cachexia, though several other potential mediators have been identified." (PMID 33330108, 2020). "Cumulated studies have shown that serum cytokines such as IL-6 and TNF-α are elevated in cachexia mice and NF-κB played a vital role in muscle wasting." (PMID 31615487, 2019). "Prolonged exposure to low concentrations of TNF-α can result in cachexia, a wasting syndrome, which can be found in cancer patients." (PMID 31842409, 2019).
Cachexia (continued). "There exists considerable evidence suggesting TNF-a and IL-6 are the most relevant cytokines inducing muscle wasting and promoting the development of cachexia." (PMID 31615487, 2019). "TNF‐α also induces the ubiquitin‐proteasome system in cachexia, which can be attenuated by blocking the activation of NFκB signaling." (PMID 30256507, 2018). "IL-6 and TNF-α further contribute to cachexia by stimulating muscle catabolism via the activation of proteasome pathways." (PMID 29631586, 2018). "Among potential mechanisms involved in the development of cachexia, the primary initial process is probably the systemic inflammatory response followed by increased production of pro-inflammatory cytokines, such as TNF-α." (PMID 29802455, 2018). "According to recent studies, miRNA-130a is involved in the regulation of TNF-α expression; therefore, it seems to be an attractive cachexia marker related to regulation of inflammatory response." (PMID 30200243, 2018). "The detection of cachexia followed by high TNF-α level ROC demonstrated: 83.3% sensitivity and 91.7% specificity (AUC = 0.931 (0.794–0.988); p < 0.001)." (PMID 30200243, 2018). "An additional and important point to be considered concerning TNFα is its close relationship with the phenomena of cachexia and its potent anorexigenic action in the hypothalamus." (PMID 29959379, 2018). "In our study, we examined miRNA-130a as a cachexia predictor involved in the regulation of inflammatory response via targeting TNF-α." (PMID 30200243, 2018). "Basing on a study set, the new cachexia related SNPs were revealed, and among them the TNF-α −1031T/C." (PMID 29802455, 2018). "Increased IL-6, IL-8, and TNF-α level were also found in gastrointestinal cancer patients with cachexia." (PMID 30513776, 2018). "LIF is a tumor-derived factor that is involved in the development of cachexia/anorexia, alongside IL-6 and TNFα." (PMID 30513935, 2018). "The primary catabolic mediators of cachexia include proinflammatory cytokines such as tumor necrosis factor alpha (TNFα), interferon gamma (IFNγ), and interleukin‐6 (IL‐6)." (PMID 28264935, 2017). "IL-6 and TNF-α further contribute to cachexia by stimulating muscle catabolism through the activation of the ubiquitin-proteasome pathway." (PMID 28764778, 2017). "In theory, anti-TNF therapy is expected to be effective to treat or prevent cachexia in patients with rheumatic disorders." (PMID 27401188, 2016). "It has been reported that, in cachexia, tumor-derived inflammatory cytokines such as IL-6, TNF-α, and IL-1 are critical inducers of muscle wasting and fat depletion." (PMID 27064118, 2016). "Instead, we uncover a prominent role of IL-6, a key mediator of TNF- and inflammation-induced cachexia." (PMID 27523608, 2016). "TNF-α is a potent inducer ofmuscle metabolism and cachexia by stimulating lipolysis and inhibiting lipoproteinlipase." (PMID 27759779, 2016). "At the clinical level, TNF-α induces fever, asthenia, cachexia, and hypertriglyceridemia; additionally, increased serum TNF-α levels contribute to the hypergammaglobulinemia observed in trypanosomiasis." (PMID 28082973, 2016). "TNF-α (formerly called cachectin), a pivotal cytokine in rheumatic diseases, plays an important role in the development of cachexia." (PMID 27401188, 2016). "The levels of serum IL-6 and IL-1β in the group receiving high-dose docetaxel increased, whereas the levels of TNF-α in all groups were more or less the same, suggesting that the docetaxel-induced cachexia differs from the tumor-induced cachexia." (PMID 25797259, 2015). "Cytokines greatly influence development of cachexia, in which proinflammatory cytokines TNF-α and IL-6 play a much greater role." (PMID 25797259, 2015). "Both cachectic cancer patients and animal models of cachexia have elevated proinflammatory cytokine (e.g. TNFα, IL-1, IL-6) expression in the bloodstream, suggesting that these factors play a role in the development of cachexia." (PMID 26709824, 2015).
Cachexia (continued). "Proinflammatory cytokines such as IL-1 and TNFα have been recognized for many years as principal actors in the pathogenesis of anorexia and cachexia." (PMID 26504362, 2015). "The increased production of proinflammatory cytokines, mainly IL-1β and TNF-α, seems to be involved in inflammatory cachexia and induces the production of prostaglandin E2 (PGE2), which plays an important role in the inflammatory response." (PMID 26064425, 2015). "Another explanation is that a cytokine like TNF-α is involved in early stages of cachexia but is transient in nature." (PMID 25415607, 2014). "Macrophages appear to be the source of some of the principal mediators of cachexia, such as TNF-α or IL-1." (PMID 24877061, 2014). "TNF-α was initially thought to play a direct role in cachexia by inhibiting lipoprotein lipase and enhancing the protein degradation." (PMID 24877061, 2014). "Elevated levels of serum inflammatory cytokines, such as IL-6, TNF-α and IFNγ, have been shown to impact myogenic and nuclear receptor signaling pathways in cancer-induced cachexia." (PMID 24782788, 2014). "Chronic exposure to low levels of circulating TNF inhibits muscle regeneration and induces cachexia." (PMID 24971321, 2014). "The direct correlation between TNF-α levels and the degree of cachexia has been more difficult to prove, however." (PMID 24877061, 2014). "Other experimental studies show that high levels of TNF-α in the acute phase seem to lead to cachexia and death, becoming an essential element of tissue inflammatory reaction." (PMID 25050370, 2014). "Because TNF can induce cachexia, we investigated the extent to which inTNF administration decreased food and water intake." (PMID 23622116, 2013). "Disturbances in the feedback mechanism in the hypothalamus and/or release of pro-inflammatory cytokines, such as IL-1, IL-6, and TNF-α, are thought to be responsible for cachexia in this setting." (PMID 22518191, 2012). "For TNF-α there was a significant interaction with cachexia at baseline in patients with sustained high TNF-α at year 0 and year 1 (p = 0.001)." (PMID 22708547, 2012). "We addressed this question both in vitro using differentiated myotubes treated with TNF-α, and in vivo in a murine model of tumor-induced cachexia." (PMID 22257771, 2012). "In the Yoshida AH-130 model, anti-TNF therapy partially reversed metabolic abnormalities in cachexia." (PMID 22518191, 2012). "Although our HIV-1 transgenic rat model is not an infectious model, HIV-1 transgenic rats show signs that are typical for chronic infections including cachexia and a dramatic increase in liver-specific expression of TNFα." (PMID 21978457, 2011). "Mice implanted with Chinese hamster ovary (CHO) cells transfected with a human TNFα vector develop cachexia and die sooner than mice implanted with CHO cells transfected with a control vector alone." (PMID 21832306, 2011). "Levels of Tumor Necrosis Factor (TNF), IFN-γ and IL-1α, three other cytokines frequently associated with cachexia, were significantly elevated as well." (PMID 21799891, 2011). "There is some evidence suggesting that disuse muscle atrophy induced by unloading is associated with the activation of an alternative NFκB pathway distinct from the pathway seen with cachexia where TNFα is responsible for muscle atrophy." (PMID 21843349, 2011). "Some cytokines, including TNF-α, interleukin-1 (IL-1), IFN-γ, and IL-6 have been implicated in cachexia." (PMID 22185352, 2011). "Several animal models for cachexia have shown that TNFα is one of the main cytokines that triggers muscle wasting." (PMID 21832306, 2011). "The mechanism of cachexia was believed to be related in large part to an increase in levels of tumor necrosis factor α (TNF-α), which ATP had the ability to decrease." (PMID 21675943, 2011). "Several drugs targeting TNFα signaling have been investigated for their potential use in the treatment of cachexia." (PMID 21832306, 2011).
Cachexia (continued). "Tumour necrosis factor (TNF, former designated TNF-α) and lymphotoxin (LT; former TNF-β) were for many years also known as cachectin from their involvement in cachexia of cancer patients." (PMID 16076403, 2005). "Spleen TNF-α, in particular, is significantly correlated with the severity of the wasting syndrome in adjuvant arthritis." (PMID 15899031, 2005). "Furthermore, TNF-α and IL-1 can enhance the activation of the IL-6 signaling pathway, further exacerbating the progression of cachexia." (PMID 41526343, 2026). "However, the overall effectiveness of TNF-α inhibition is limited due to the complex interaction of various cytokines involved in cachexia." (PMID 40519290, 2025). "However, evidence supporting the efficacy of anti‐TNF‐α therapy for treating cachexia in humans remains limited." (PMID 39764565, 2025). "Previous studies linked high extracellular TNF-α levels to non-surviving patients with septic shock, cachexia and death in HIV patients, whereas intracellular TNF-α induces an NF-κB gene activation cascade that promotes fibrosis formation." (PMID 40507635, 2025). "Additionally, inflammation activates pro-inflammatory cytokines, such as IL-6 and TNF-α, which contribute to muscle breakdown and cachexia, leading to worsened clinical outcomes and increased mortality." (PMID 40597895, 2025). "Moreover, in the course of cachexia, browning of adipose tissue is observed, which is mainly mediated by proinflammatory cytokines, e.g., TNF-α, IL-6, and IL-1β." (PMID 38610941, 2024). "This may be due to the fact that in NSCLC patients with cachexia, IL-6, IL-1, and TNF-α reduce CD8+ tumor infiltrating lymphocytes and anti-tumor immunity." (PMID 38466657, 2024). "Among these factors, TNF-α is the first factor confirmed to be related to cancer-related cachexia." (PMID 39114348, 2024). "Given that TNF-α is another main stimulator of muscle wasting, we conducted an assessment to ascertain whether DH could replicate similar effects in an in vitro cachexia model induced by TNF-α." (PMID 38556548, 2024). "Despite several roles of IL-6 in the context of cachexia, the exclusive targeting of IL-6 may encounter similar obstacles as anti-tumor necrosis factor (anti-TNF) therapy." (PMID 38334644, 2024). "Catabolic processes in cachexia are commonly governed by proinflammatory cytokines such as TNF." (PMID 38337428, 2024). "Nevertheless, evidence suggests that sophocarpine can mitigate cancer-induced cachexia by concurrently reducing the levels of TNF-α and IL-6 in RAW264.7 cells and macrophages, indicating the possible involvement of inflammatory cytokines in the antitumor effects exerted by sophocarpine." (PMID 38746009, 2024). "We employed an in vitro cachexia model using mouse cancer ascites, which contained TNFα and HMGB1." (PMID 39796128, 2024). "In this regard, the present study is the first to investigate the effects of OC on myotube cultures exposed to stimuli able to mimic a pathological muscle microenvironment, namely the pro-inflammatory cytokine TNF-α or the medium conditioned by a cachexia-inducing experimental tumor." (PMID 38732549, 2024). "In the piglet model with LPS-induced cachexia, the morphological and ultrastructural damage, and the release of pro-inflammatory cytokines including tumor necrosis factor (TNF)-α, interleukin (IL)-1β, and IL-6 were dynamically elicited in longissimus dorsi muscle." (PMID 37446099, 2023). "The myogenic regulatory factors, myogenic differentiation factor (MyoD) and myogenin, which are controlled by AKT phosphorylation, p38, myostatin and TNF‐α, have been demonstrated to play a significant role in tumour‐induced cachexia by controlling muscle regeneration." (PMID 37661635, 2023). "In addition, both factors were associated with levels of different cytokines, namely CRP with interleukin-1β, a driver of MF pathogenesis, and albumin with TNF-α, a key mediator of cachexia." (PMID 36900271, 2023).